DSN1 (DSN1 component of MIS12 kinetochore complex)
Diseases named in the same sentence as DSN1 in open-access papers (continued):
Sharing a sentence is not in itself a finding about the gene and the disease.
tumor (7 papers, 2016 to 2025). "DSN1 was also closely associated with tumor-infiltrating immune cells and immune-regulatory genes, as well as immune therapy response and drug sensitivity." (PMID 40535813, 2025). "We also examined the correlation of DSN1 with DNA methylation, tumor mutation burden (TMB), microsatellite instability (MSI), immune infiltration, and immune-regulatory genes." (PMID 40535813, 2025). "DSN1 expression was associated with tumor staging in ACC, KIRP, LIHC, and SKCM, and high DSN1 levels were linked to increased recurrence risk in ACC, BLCA, LGG, LIHC, PRAD, SARC, and UVM." (PMID 40535813, 2025). "In most cases, high DSN1 is associated with reduced infiltration of most immune cell types, potentially facilitating immune evasion by rapidly proliferating tumor cells." (PMID 40535813, 2025). "High DSN1 expression (as a centromere component) is associated with the activation of cell proliferation pathways and cell cycle progression, potentially promoting genomic instability that triggers DNA damage checkpoints or apoptosis, thereby contributing to tumor growth and progression." (PMID 40535813, 2025). "Next, we utilized the CPTAC protein expression data from the UALCAN database 18 to compare DSN1 protein levels in normal and tumor tissues." (PMID 40535813, 2025). "To further explore the significance of DSN1 in tumor microenvironment (TME) immunotherapy, we analyzed the correlation between DSN1 expression and tumor mutational burden (TMB) as well as microsatellite instability (MSI)." (PMID 40535813, 2025). "According to the box diagram in the GEPIA database, the mRNA expression level of DSN1 in tumor tissues was significantly higher than that in normal control tissues." (PMID 39555702, 2024). "The results of the co-expression and GSEA indicated that DSN1 is highly correlated with tumor proliferation, which further confirms the credibility of our research." (PMID 39555702, 2024). "Third, the correlation module results showed that DSN1 was related to some well-known tumor immune-related biomarkers, such as PDCD1, CD274, PDCD1LG2, and CTLA4." (PMID 39555702, 2024). "Our data for 16 CRC clinical tissue samples also showed that the mRNA and protein levels of DSN1 were noticeably elevated in tumor tissues." (PMID 35509101, 2022). "The expression of DSN1 is obviously higher in primary tumor with various stages and grades than normal tissues." (PMID 34131395, 2021). "We also identified DSN1, the overexpression of which was driven by chromosome 20q gain, as an additional gene critically involved in tumor progression." (PMID 27329586, 2016). "Collectively, these data suggest that DSN1 may be actively involved in the cellular processes that underpin tumor development." (PMID 40535813, 2025). "Importantly, the expression of DSN1 is related to many types of tumor-infiltrating immune cells and has a positive correlation with PDL1." (PMID 39555702, 2024). "This suggests that DSN1 may be involved in tumor proliferation." (PMID 39555702, 2024). "Notably, PD1 is related to tumor immune escape; therefore, we suspect that DSN1 may be involved in this process." (PMID 39555702, 2024). "MGC 803/Lv-shESRRA had impaired ability in tumor formation when comparing with MGC 803 Lv-shNC, but MGC 803/Lv-shESRRA+DSN1 rescued to a degree." (PMID 34131395, 2021). "To reveal the relationship between DSN1 and LGG immune cell infiltration, through the “gene” module in the Tumor Immune Estimation Resource (TIMER) library, we found that the infiltration of some immune cells in LGG was positively related to the expression of DSN1." (PMID 39555702, 2024). "The analysis of 10 DSN1 transcripts, including 7 protein-coding, 3 non-coding ones showed that, almost all protein-coding transcripts were upregulated in most tumor tissues, while non-coding ones did not exhibit a clear pattern of upregulation or downregulation." (PMID 40535813, 2025).
DSN1 also shares sentences with these, for which no sentence is quoted: cervical cancer (2 papers); liver cancer (2); gallbladder cancer (1); osteosarcoma (1); pancreatic adenocarcinoma (1); polyp (1); renal cell carcinoma (1); salivary gland cancer (1).